IL21 (interleukin 21)
Diseases named in the same sentence as IL21 in open-access papers (continued):
Sharing a sentence is not in itself a finding about the gene and the disease.
autoimmune disease (continued). "Alongside these findings, animal studies demonstrate that IL-21R deficient mice have normal T-cell and NK cell development but fail to develop spontaneous autoimmune disease suggesting that IL-21 plays a vital role in the development of autoimmune disease in rodents." (PMID 20553587, 2010). "Known its regulatory role, IL-21 could be used as a therapeutic target: the development of compounds neutralizing IL-21 (such as blocking antibodies or recombinant proteins) constitutes an exciting therapeutic arm for autoimmune diseases." (PMID 37432371, 2023). "IL-21 has a variety of effects on the immune system and plays a critical role in B-cell responsiveness, proliferation, plasma differentiation, and immunoglobulin production; thus, the IL-21 effects on B cells may contribute to the development of autoimmune diseases." (PMID 37107636, 2023). "In the AN context, given the variety of effects that IL-21 has on the immune system, IL-21 could act as a stimulant of the immune response determining the initiation and progression of inflammatory reactions involved in several autoimmune diseases." (PMID 37432371, 2023). "Notably, affected by a variety of cytokines released during autoimmune responses including IL-21, IL-4 and IFN-γ, Tfc cells produce IL-21, which furtherly induces plasma cell differentiation and antibody class switching, constructing a positive feedback loop in autoimmune diseases." (PMID 36591286, 2022). "Interestingly, the median IL-21 level was 0 pg/mL, which could mean IL-21 is only produced in response to autoantibodies in autoimmune diseases, while the level of IL-21 produced by healthy adults is below the detection limit." (PMID 35265152, 2022). "Knowledge of the biological functions of IL-21 has led to clinical trials using this cytokine alone or in combination with other agents in treating metastatic cancers, and blocking antibodies to IL-21R are now being evaluated in clinical trials for the treatment of autoimmune diseases." (PMID 26966515, 2016). "So far, such studies have not been conducted, but based on the biological functions of IL-21, the promising findings in animal models for autoimmune diseases and in vitro studies, targeting the IL-21 pathway could be expected to reduce the incidence of antibody-mediated alloreactivity." (PMID 27602031, 2016). "Thus, although blocking IL-21 signaling is currently under evaluation in early clinical trials for the treatment of autoimmune disease, it conceivably could have mixed effects depending on the context in individual patients." (PMID 26966515, 2016). "Levels of IL-21 and IL-21R could be quite different in patients with autoimmune diseases." (PMID 23496892, 2013). "And the evident increase of serum IL-21 level in primary Sjogren’s syndrome (pSS) patients has positive correlation with the levels of gamma-globulin and erythrocyte sedimentation rate.These suggests that IL-21 and IL-21R may play a critical role in the pathogenesis of autoimmune diseases." (PMID 23889847, 2013). "Thus, IL-21 seems to play an important role in autoimmune diseases in general and could constitute a novel target for therapy." (PMID 23799890, 2013). "However, whether IL-21 is involved in the development of uveitis, a typical autoimmune disease, and whether it can regulate IL-17 production in EAU, are still unknown." (PMID 20057909, 2009). "These effector TH17 cells produce predominantly IL-17, IL-21, and IL-22 plus factors like nitric oxide, matrix metalloproteinase, and prostaglandin E2, each of which is shown to play an important role in the immunopathophysiology of several autoimmune diseases, including SjS." (PMID 19032782, 2008). "This is consistent with the effects of IL-21R blockade on the outcome of pMHCII-NP therapy in various autoimmune disease models where we have documented TR1 cell-driven, IL-21-dependent Breg cell formation." (PMID 35672409, 2022).
autoimmune disease (continued). "The main function of Th17 cells is to produce various cytokines, such as IL-17, IL-21 and IL-22, which stimulate epithelial cells, fibroblasts and smooth muscle cells of the airway to secrete CXCL1 and CXCL8, thereby participating in autoimmune diseases." (PMID 34863307, 2021). "Our patients demonstrated elevations of five biomarkers of inflammation (IL-1β, IL-21, TNFα, INFγ, and CD30) that are known to be elevated in autoimmune disorders such as RA and SLE." (PMID 33562074, 2021). "In systemic lupus erythematosus, an autoimmune disease with a humoral component, TLR-stimulated HSC produce IL-17 and IL-21 and expand Th17 and Tc17 cells, contributing to disease severity." (PMID 33424854, 2020). "IL-21 uniquely contributes to SLE and other autoimmune diseases, because pharmacological and genetic abrogation of IL-21 signaling in mice stopped inflammation in non-lymphoid organs and protected them from autoimmune diseases, respectively." (PMID 32441253, 2020). "The microenvironment in patients with autoimmune diseases is very complex and encompasses a series of pro‐inflammatory cytokines such as IL‐6, TNF‐α, IL‐21 and IFN‐γ." (PMID 32881301, 2020). "IL‐21, a CD4+ T cell–derived cytokine, is shown to enhance inflammatory response in autoimmune disease." (PMID 32881301, 2020). "Given that most of the IF-specific T cells found at gastric level secreted interleukin 21 and interleukin 17 we can speculate that Th17 cytokines are very important for driving gastric autoimmunity and autoantibody production in PA patients, as it is the case in many autoimmune diseases." (PMID 31080562, 2019). "Although our studies suggest that IL-21 could be exploited as an immunotherapeutic agent for the restoration of essential immune system functioning following ablative therapy, its impact on inducing/promoting autoimmune diseases in BMT patients remains elusive." (PMID 28615039, 2017). "Th17 cells, a key player in autoimmune diseases and antibiosis, are differentiated from naïve T cells (CD4+) stimulated by IL-6, TGF-β, IL-1β, IL-21 and IL-23 and release IL-17A, IL-17F, IL-21 and IL-22." (PMID 28899359, 2017). "Increasing IL-21 levels in blood have been previously observed in MG and other auto-ab-mediated autoimmune diseases, such as RA and SLE suggesting that IL-21 is produced by autoreactive Tfh cells during an ongoing auto-ab response." (PMID 26872212, 2016). "Th17 cells are characterized by the production of various proinflammatory cytokines including IL-6, IL-17, IL-21, and TNF-α, and play crucial roles in the pathogenesis of various autoimmune diseases, including RA." (PMID 26544846, 2015). "IL-21 is produced by NKT and CD4+ T cells and plays an important role in the development of autoimmune diseases and is confirmed as a potent antitumor agent in animal models." (PMID 23741351, 2013). "Thus, the effect of IL-21 on B cells may contribute to the development of autoimmune diseases." (PMID 23176102, 2012). "To further investigate its function, we analyzed the role of IL-21 in EAU, a typical T-cell-mediated autoimmune disease." (PMID 20057909, 2009). "Importantly, IL-21 blockade could represent an important therapeutic target to control T cell survival and homeostatic expansion, leading to novel treatment strategies for autoimmune diseases as well as immunodeficiencies." (PMID 18773086, 2008). "By understanding these interactions, Tfh pathways may serve as potential therapeutic targets, with IL-21, ICOS, and PD1 blockades emerging as promising innovative therapeutic strategies to manage autoimmune diseases." (PMID 40283219, 2025). "Indeed, in some autoimmune diseases, such as Sjögren’s syndrome and systemic lupus erythematosus (SLE), plasma and/or serum IL-21 levels are elevated in patients." (PMID 37415982, 2023).
autoimmune disease (continued). "To determine whether the suppression of IL-4 and IL-21 induced downstream pathways could serve as a strategy to treat autoimmune diseases, we used three JAK inhibitors to suppress IL-4/STAT6 and IL-21/STAT3 activation in anti-IgM-treated Ramos cells." (PMID 35911775, 2022). "Cytokines and chemokines that we found elevated in POTS patients, in contrast to our non-POTS group, and that have been related to autoimmune diseases, include not only IL-21, but also IL-1β, INFΥ, CD30, and IL-17." (PMID 35269395, 2022). "Dysregulation of B cells and autoAb production in SLE-like autoimmune disease are influenced by both innate (TLR) and adaptive (CD40) pathways and Tfh secreted IL-21 which regulates B cell differentiation into plasma cells, memory B cells and CD11chi ABC B cells." (PMID 34512628, 2021). "Particularly, exercise training induced a tendency to decrease all cytokines, with someone reaching significance, including the proinflammatory IL8 and both IL21 and IL22 produced by Th17 cells, which play a critical role in the pathogenesis of autoimmune diseases." (PMID 34853628, 2021). "In addition, IL-21 has essential non-redundant regulatory functions on B cell responses and can promote B cell differentiation and antibody production, indicating that IL-21 may also be a causative factor in autoimmune diseases." (PMID 24944624, 2014). "Moreover, Th17 and some cytokines such as IL17, IL21, IL27, IL35, and IL37 are recognized well in autoimmune diseases, though their possible roles as therapeutic target in GBS need to be further explored." (PMID 25614713, 2014). "Notably, aberrant methylation patterns of IL-17, IL-21, and IL-22 are not exclusive to GD; similar patterns have been reported in other Th17-mediated autoimmune diseases, including rheumatoid arthritis, psoriasis, and Sjögren’s syndrome." (PMID 41035651, 2025). "Moreover, IL-21 not only induces the differentiation of B cells into plasma cells, but also promotes the proliferation of germinal center B cells and antibody production through CD40L/CD40 interaction, thus participating in autoimmune disorders." (PMID 34669781, 2021). "IL-21 and IL-6 together could induce CD4+CXCR+PD-1+ Tfh cell differentiation, and this Tfh cells could promote immunoglobulin production form B cells, thus Tfh cells could be a therapeutic target for treatment of autoimmune disease." (PMID 30760702, 2019). "In summary, increase in Tfh cells rather than Th17 cells is correlated with auto-reactive autoimmune disease in BXD2 mice, and thus targeting Tfh cells, such as blocking IL-21, rather than Th17 cells, would be beneficial for the treatment of antibody-mediated autoimmune diseases in humans." (PMID 25768299, 2015). "Adding IL-21 to PBMC cultures could increase Tfh cell numbers in vitro, which was down-regulated when cocultured with dexamethasone in a dose-dependently manner, suggesting that Tfh cells could be a new therapeutic target for autoimmune disease." (PMID 23284839, 2012). "Thus, it is possible that IL-21 is involved at the onset of autoimmune disease rather than later during the active systemic inflammation stage." (PMID 22030011, 2011). "The Th17 cell is newly characterized by secretion of IL-17, IL-22, and IL-21 with or without IFN-γ, and its function is opposite to that of the Treg cell in autoimmune disease since Th17 cells usually promote inflammatory processes." (PMID 20064222, 2010).
lupus (125 papers, 2006 to 2026). "A previous study discovered that in a lupus susceptible mouse model, elevated levels of IL-21 resulted in the accumulation of immune complexes in the glomeruli, thickness of the glomerular basement membrane, and proteinuria." (PMID 39464895, 2024). "IL-21 has also been shown to play a pathogenic role in mouse models of lupus and rheumatoid arthritis." (PMID 38164992, 2024). "Together, these observations lend further support for the use of iLD-IL-2 in T1D as well as in other diseases associated with increased IL-21 production, such as systemic lupus erythematosus, rheumatoid arthritis, and psoriasis." (PMID 36443294, 2022). "Previous studies have also shown that IL-21 is associated with the severity of diseases such as systemic lupus erythematosus, rheumatoid arthritis, type 1 diabetes, and Sjogren's syndrome." (PMID 33123078, 2020). "IL-21 has been shown to have a pathogenic role in several lupus-prone mouse models and its blockade with anti-IL-21 reduced disease progression." (PMID 30013031, 2018). "Herber, D.; Brown, T.P.; Liang, S.; Young, D.A.; Collins, M.; Dunussi-Joannopoulos, K. IL-21 has a pathogenic role in a lupus-prone mouse model and its blockade with IL-21R.Fc reduces disease progression." (PMID 31557991, 2016). "IL-21 is one of several cytokines associated with systemic autoimmunity and has been linked with lupus pathogenesis in mice and humans." (PMID 24470500, 2014). "The lupus-susceptibility gene IL21 rs907715, identified in European descent, was replicated in current study." (PMID 23236436, 2012). "Previous studies established and confirmed the genetic association between IL21 and lupus in European descent." (PMID 23236436, 2012). "This could provide a mechanistic explanation for the association of polymorphisms in Il21 and Il21r and increased IL‐21 production with systemic lupus erythematosus (SLE)." (PMID 35801309, 2022). "IL-21 is another proinflammatory cytokine that mediates antibody class switching and production, and this cytokine has pathogenic effects in (auto)immune disorders, including Sjogren’s syndrome, systemic lupus erythematosus, and psoriasis." (PMID 36256663, 2022). "IL-21/IL-21R blockade is associated with decreased IL-6 and autoantibody production and has shown positive effects in preclinical trials in murine models of lupus and rheumatoid arthritis." (PMID 30984195, 2019). "Finally, a genetic association with systemic lupus erythematosus and two SNPs located within the IL-21 gene was found in a case–control study (1,318 cases and 1,318 controls)." (PMID 19302705, 2009). "Th17-lymphocytes are highly efficient producers of IL-21, IL-22, and especially IL-27; cytokines widely associated with the development of pathologies such as Systemic Lupus Erythematosus (SLE), RA, and Multiple Sclerosis (MS)." (PMID 32384594, 2020). "Considering the heterogeneity of lupus patients, the efficacy of anti-IL-21 antibody on Act1-deficient mice implicates that this mouse strain can be further exploited as a specific model for testing anti-IL-21 as a potential therapy for SLE patients with the SNP-D10N Act1 mutation." (PMID 30013031, 2018). "First hypotheses regarding the role of TFH cells in SLE development are based on studies using mice deficient for Roquin1 (a negative regulator of ICOS mRNA stability) in which an excessive number of TFH cells and GC reactions and high levels of IL-21 are associated with a lupus-like phenotype." (PMID 27635407, 2016). "IL-21 accumulated in lupus-like lesions and elicited CD11b B cell differentiation, whereas the ABC differentiation was slightly influenced." (PMID 39960645, 2025). "Regarding the mechanisms of B cell involvement in lupus lesions, studies have shown that autoreactive B cells can be recruited into the tissue in response to inflammatory signals such as interferon, IL-21, and TLR7/9." (PMID 39917309, 2025).
lupus (continued). "For example, IL-21 and IL-17 levels are elevated in patients with systemic lupus erythematosus (SLE) due to the expansion of Th17 cells and the reduction of Tregs." (PMID 40061938, 2025). "In humans, overproduction of IL-21 has been noted in multiple autoimmune conditions including type 1 diabetes, rheumatoid arthritis and systemic lupus erythematosus (SLE)." (PMID 38164992, 2024). "Experimentally, it has been proven that IL-21 is necessary for B cell expansion, class switching, and plasma cell development during lupus-like onset in animal models." (PMID 39124778, 2024). "An increasing body of evidence supports the notion that IL-21 plays a central role in influencing CD11c+ ABCs in lupus patients, potentially enhancing the involvement of CD11c+ ABCs in the pathogenesis of pSS." (PMID 38398810, 2024). "In fact, IL‐21 increases the recruitment of TET2 to the BCL6 promoter region in lupus patients, while interferon (IFN)‐α, the signature cytokine for lupus, also increases AIM2 levels, albeit to a lesser degree." (PMID 35538881, 2022). "Our previous studies revealed that TET2 enrichment on the BCL6 promoter was attributed to IL‐21, which potentially explains why lupus T cells have higher BCL6 expression." (PMID 35343082, 2022). "Pristane-induced lupus mice showed significantly higher serum levels of IL-1β, IL-2, IL-4, IL-13, IL-21, and IL-22 compared to those in WT mice." (PMID 35911685, 2022). "In an MRL-Fas(lpr) lupus murine model, blocking the IL-21 signal with an IL-21R.Fc fusion protein reduced the phenotypic disease severity, such as proteinuria, skin lesions, as well as renal injury and autoantibody production." (PMID 36293075, 2022). "Another study with lupus-prone B6.Sle1.Yaa mice showed that treatment with an anti-IL-21 blocking antibody reduced titers of autoantibodies, decreased renal infiltrating TFH cells and delayed the progression of glomerulonephritis." (PMID 36293075, 2022). "We demonstrated that the overexpression of BCL-6 in CD4+ T cells in lupus decreased the expression of miR-142-3p/5p, and inhibition of miR-142-3P/5P, and led to increased expression of IL-21." (PMID 35637283, 2022). "In humans, a study investigated the importance of IL-21 in SLE and found that CD4+ T cells producing IL-21 were elevated in patients with lupus, and it associated positively with the ratio of Th17 cells." (PMID 36293075, 2022). "IL‐21 can enhance the recruitment of the hydroxymethyltransferase TET2 in the promoter region of BCL6 in lupus patients." (PMID 35343082, 2022). "c-Maf, a transcription factor downstream of IL-21 signaling, was expressed in lupus Tph cells, suggesting the importance of c-Maf in the upregulation of IL-21 expression and its participation in the pathogenesis of SLE." (PMID 35755031, 2022). "Further examination of B cell differentiation in response to IL-21/IL-21R inhibition in a larger cohort of lupus patients with different clinical manifestations would be beneficial in the future." (PMID 36293075, 2022). "GDF-15 treatment significantly reduced levels of IL-1β, IL-2, IL-4, IL-21, and IL-22, by which treatment of lupus mice with 100 μg/kg GDF-15 had the most efficiency." (PMID 35911685, 2022). "A similar increase in IL-21 levels and Bacteroidetes abundance together with a low Firmicutes/Bacteroidetes ratio as observed in the inflammatory disease Systemic Lupus erythematosus supports this idea." (PMID 34199203, 2021). "CD27-IgD-CXCR5- (DN2) B cells are capable of differentiating into plasma cells induced by IL-21 in lupus patients." (PMID 34168653, 2021). "In a murine model of lupus, the blockade of IL-21/IL-21R showed a reduction in B and T cell activation together with an interruption of disease progression." (PMID 33801294, 2021). "IL-6 and IL-21 are pro-inflammatory cytokine for lupus progression, and also important regulators of TFH cell generation." (PMID 33632240, 2021).